PRL (prolactin)
Diseases named in the same sentence as PRL in open-access papers (continued):
Sharing a sentence is not in itself a finding about the gene and the disease.
pituitary tumor (continued). "In the overall sample, 73 patients had confirmed diagnosis of a prolactinoma, three had plurihormonal (prolactin and growth hormone) secreting tumors, 13 had non-functioning pituitary tumors (NFPA), and 14 had acromegaly." (PMID 33193096, 2020). "Prolactin-secreting pituitary tumors are called prolactinomas and are highly prevalent along with non-functioning pituitary tumors." (PMID 29104246, 2017). "Recently, a role for cytoskeleton protein filamin A (FLNA) in DRD2 and SSTRs receptors expression and signaling in PRL- and GH-secreting tumors, respectively, has been demonstrated, first revealing a link between FLNA expression and responsiveness of pituitary tumors to pharmacological therapy." (PMID 26733942, 2015). "Low expression of β-arrestin 1, but not β-arrestin 2, in GH- and PRL-secreting pituitary tumors correlates with a reduced recycling rate of SSTR2 and better SS analogs response in terms of GH suppression, both in vitro and in vivo." (PMID 26733942, 2015). "More than 75% of the pituitary tumors contained prolactin, GH and ACTH, and the remainder were considered nonfunctioning tumors." (PMID 25870702, 2014). "On the one hand, prolactin enhances PPARγ and C/EBPβ mRNA production and augments adipocytes differentiation in NIH-3T3 cells; on the other hand, TZDs activation of PPARγ inhibits prolactin function in pituitary tumor cells." (PMID 22135675, 2011). "Thus, the findings of our study indicate that macroprolactin is worth screening in all patients with pituitary tumors and prolactin < 500 ng/mL, regardless of their clinical presentation." (PMID 39420933, 2024). "One should consider that this group of tumors might be part of immature pit1-lineage tumors (2022 WHO Classification of Pituitary Tumors) with focal or variable staining for no hormones or one or more of GH, PRL, and TSH." (PMID 36518240, 2022). "However, the literature indicates that after treatment with cabergoline, serum prolactin and oestrogen decreased and ovarian cysts shrank, but pituitary tumours did not shrink." (PMID 34248835, 2021). "In addition, EGF could also induce prolactin (PRL) synthesis and reduce growth hormone (GH) synthesis in rat pituitary tumor cells." (PMID 31635309, 2019). "We had also previously shown that a 10 nmol/l 17α-estradiol concentration could elicit another type of nongenomic estrogenic effect in our GH3/B6/F10 pituitary tumor cell model – rapid prolactin release." (PMID 15642162, 2005). "Besides the proband (IV:4), nonfunctioning pituitary tumors were identified in three carriers of the CDKN1B variant, including two microadenomas (III:4 and III:7) and one macroadenoma (IV:1), with functionality classified on the basis of measurements of IGF-1 and prolactin." (PMID 30990521, 2019). "Pituitary tumors MEN1 mice, one year old were immunoreactive for PRL, but not for other pituitary hormones." (PMID 25870702, 2014). "The MEN1-KO pituitary tumors were prolactinomas and unlike non-tumoral pituitary tissue of MEN1-KO, displayed no PRL-FSH colocalization." (PMID 25870702, 2014). "In addition, expression of Gαi proteins was studied in human growth hormone (GH), prolactin (PRL), adrenocorticotropic hormone (ACTH)-secreting and non-functional pituitary tumors." (PMID 25291362, 2014).
schizophrenia (144 papers, 2004 to 2025). A major psychotic disorder characterized by abnormalities in the perception or expression of reality. "Antipsychotics, widely used in schizophrenia, frequently cause ED through dopamine inhibition and increased prolactin levels, affecting libido and erectile capacity." (PMID 41146786, 2025). "Risperidone or paliperidone ranked highest in terms of associated change in prolactin, which is consistent with the conclusion of a previous, smaller meta-analysis in paediatric patients with schizophrenia and schizophrenia spectrum disorders." (PMID 38897716, 2024). "Both were limited to children and adolescents with a diagnosis of schizophrenia and concluded that antipsychotic treatment was associated with bodyweight gain and increased prolactin." (PMID 38897716, 2024). "The initial elevation in serum PRL levels can be seen as an organism’s response to stress, with an association between elevated serum PRL levels and the onset of schizophrenia." (PMID 39267697, 2024). "Antipsychotic medications, which schizophrenic patients with schizophrenia usually take for years, are associated with increased prolactin levels, which can cause osteoporosis." (PMID 38868087, 2024). "The most common cause of impaired PRL secretion in schizophrenia patients is antipsychotic treatment." (PMID 36833950, 2023). "In turn, prolactin secretion results in estrogen deficiency and dopamine stimulation, further exacerbating schizophrenia symptoms." (PMID 36979271, 2023). "Blonanserin significantly improved the symptoms of schizophrenia in female patients aged 18–40 years; the drug was well tolerated and had a low tendency to cause metabolic side effects, including prolactin elevation in these patients." (PMID 36810039, 2023). "Given the role of prolactin in metabolic homeostasis and lipid metabolism, the risk of metabolic syndrome in persons with schizophrenia depends on the prolactin levels that resulted from different antipsychotics." (PMID 35806096, 2022). "Mildly elevated prolactin levels were associated with higher total PANSS scores in first-episode untreated women with schizophrenia." (PMID 35144626, 2022). "Recently, a nationwide study in Finland demonstrated that the long-term use of PRL-increasing antipsychotics is significantly associated with the increased risk of breast cancer in females with schizophrenia." (PMID 36313772, 2022). "It has previously been shown that there is a positive association between IL-1β, IL-6, and TNF-α and prolactin levels in patients with schizophrenia." (PMID 35958655, 2022). "Differences due to gender were also evident in PRL levels in schizophrenia patients, and female was at greater risk of HPRL." (PMID 36329924, 2022). "In a previous study, we found a significant association between high aggression and high prolactin levels (PRL) in female patients with schizophrenia." (PMID 36233163, 2022). "DRD2 -141C insertion/insertion has been associated with high prolactin levels in antipsychotic-treated male schizophrenia." (PMID 34690776, 2021). "It has also been shown that the PRL level is negatively associated with the severity of positive psychosis symptoms in drug-naïve male patients with schizophrenia." (PMID 33315097, 2021). "Our study supports that the association between higher prolactin levels and sexual dysfunction in patients with schizophrenia." (PMID 34421613, 2021). "The association of lower PRL with positive symptoms was in line with the postulation that dopamine transmission was increased within this particular subgroup of schizophrenia patients." (PMID 33228575, 2020). "We believe that the selection of treatment for schizophrenia and schizophrenia-related disorders should incorporate a quantifiable risk, and thus monitoring of prolactin-related adverse events is pertinent." (PMID 29805808, 2018).
schizophrenia (continued). "The primary objective of this review is to examine the risk of prolactin-related adverse events associated with the use of antipsychotic medications for the treatment of schizophrenia and schizophrenia spectrum disorders in pediatric patients." (PMID 27825323, 2016). "First, the association between raised prolactin and acute episodes of schizophrenia needs to be replicated in larger samples." (PMID 24800074, 2014). "Blunted prolactin responses have been associated with a “Kraepelinian” diagnosis of schizophrenia and with schizophreniform disorder in particular." (PMID 24800074, 2014). "Decreased SHBG has been reported in female schizophrenia patients after treatment with atypical antipsychotics, in association with increased prolactin levels." (PMID 24244349, 2013). "Conventional antipsychotics in people with schizophrenia as well as healthy individuals cause prolactin elevations within hours of taking these agents." (PMID 23968123, 2013). "This study has provided further support to known risk factors for suicide in patients with schizophrenia, such as history of suicide attempts, male gender and depression, and has identified a novel risk factor: prolactin-related adverse events." (PMID 22812421, 2012). "Additionally, the impact on prolactin levels has been explored, with evidence suggesting that long-term AP treatment in patients suffering from schizophrenia reduces BMD, raising the risk of osteoporosis." (PMID 39682653, 2024). "This post-hoc analysis examined the effect of aripiprazole on prolactin levels in patients with schizophrenia in a real-life diagnostic environment, and analyzed whether varying baseline prolactin levels influence the effectiveness and safety of aripiprazole." (PMID 39267697, 2024). "Factors associated with PRL levels in patients with schizophrenia co-type 2 diabetes (T2DM)." (PMID 36816406, 2023). "Given that E2 stimulates OXT synthesis and release, prolactin-sparing antipsychotics that act protectively against estrogens deficiency may act against OXT dysregulation in schizophrenia as well." (PMID 36979271, 2023). "Furthermore, changes in prolactin levels are associated with symptom fluctuations in patients with schizophrenia." (PMID 37867775, 2023). "PRL was just associated with schizophrenia and mood disorders." (PMID 37252132, 2023). "The regression analysis revealed that PRL (OR = 1.1, 95% CI [1.08–1.15], P < 0.001) and E2 level (OR = 0.9, 95%CI [0.96–0.99], P = 0.011) were significantly associated with osteoporosis in patients with schizophrenia." (PMID 33987015, 2021). "It is worth noting that current studies have shown that reduced BMD in patients with schizophrenia is not only associated with elevated serum prolactin levels, but also with many other factors such as smoking, alcohol abuse, vitamin D deficiency and so on1,2,4,10,11." (PMID 32788631, 2020). "It is also hypothesized that some treatment for schizophrenia, for instance, antipsychotics, may induce higher level of prolactin and subsequently increased risk of breast cancer." (PMID 32934226, 2020). "Treatment of schizophrenia with first- and second-generation antipsychotics has been associated with elevated prolactin levels, which may increase the risk for prolactin-related adverse events." (PMID 29805808, 2018). "Specifically, the treatment of schizophrenia with risperidone may cause a substantial prolactin increase and an unacceptably high incidence of PRS, such as amenorrhea, galactorrhea, gynecomastia, and sexual dysfunction." (PMID 27829454, 2016). "According to this hypothesis, estrogen deficiency could be involved in pathogenesis of schizophrenia in women; on the other hand, estrogen may increase the serotonin-stimulated release of prolactin." (PMID 27293968, 2016). "Two recent studies have examined genetic variants in prolactin in patients with schizophrenia." (PMID 24800074, 2014).
schizophrenia (continued). "Second, the association of lower prolactin levels with positive symptoms and “paranoid” symptoms in particular are in line with the revised dopamine hypothesis of schizophrenia." (PMID 24800074, 2014). "Finally, the association of prolactin gene variants with schizophrenia—though preliminary—suggests that there is more to the schizophrenia-prolactin association than simple dopamine-based models." (PMID 24800074, 2014). "Most of conventional antipsychotics can cause prolactin elevation, Marken reported treatment with conventional antipsychotics in patients with schizophrenia has been shown to increase serum prolactin concentrations 5–10 times above that of healthy control subjects in 1992." (PMID 23690768, 2013). "Similar to risperidone, paliperidone is expected to be particularly effective against hallucination and delusion at the acute stage of schizophrenia, however, this drug is relatively likely to cause extrapyramidal symptoms and elevation in blood prolactin levels." (PMID 24090047, 2013). "Furthermore, PRL polymorphism is associated with schizophrenia, especially in male patients." (PMID 33315097, 2021). "In addition genetic studies suggested that some patients with schizophrenia may have a predisposition to HPRL consisting in functional − 1449 g/t polymorphism of the PRL gene." (PMID 30068291, 2018). "This retrospective study enrolled schizophrenia inpatients from a tertiary psychiatric hospital (2022-2023) with monitored prolactin (PRL) levels." (PMID 40964426, 2025). "Significance Statement This work analyses the sex-specific pattern of prolactin (PRL) disturbance in antipsychotic-naïve or minimally treated first-episode schizophrenia (FES), the earliest clinical manifestation of the disorder." (PMID 40971478, 2025). "For example, aripiprazole has been found to effectively and safely reduce prolactin levels in women with schizophrenia." (PMID 41008479, 2025). "A clinical study from Japan demonstrated a positive correlation between serum prolactin levels and the daily dose of paliperidone in male schizophrenia patients." (PMID 39833706, 2025). "A study of serum prolactin levels in schizophrenia found that while baseline prolactin levels were similar in unmedicated men and women, the overall prolactin response to antipsychotics was greater in women." (PMID 40817421, 2025). "Birth rates are increasing in women with schizophrenia, in part due to the use of antipsychotics that affect prolactin less and in part due to improved treatment of schizophrenia." (PMID 41008479, 2025). "Common ADEs included increased blood prolactin, galactorrhea, and schizophrenia, which was consistent with drug label." (PMID 39833706, 2025). "Studies have found that patients with schizophrenia and type 2 diabetes mellitus have lower PRL levels." (PMID 40964426, 2025). "Among 3,641 hospitalized schizophrenia patients, 2,519 (69.18%) underwent PRL monitoring during hospitalization." (PMID 40964426, 2025). "During 2022-2023, a total of 3,641 inpatient schizophrenia patients were enrolled, among whom 2,519 (69.18%) had their PRL levels monitored." (PMID 40964426, 2025). "This study revealed that only 69.18% of hospitalized schizophrenia patients underwent PRL monitoring." (PMID 40964426, 2025). "Our study revealed that treatment with aripiprazole did not result in a significant increase in serum PRL levels in patients with schizophrenia who had normal PRL levels at baseline." (PMID 39267697, 2024). "Our research highlights the importance of integrating prolactin testing into the routine monitoring regimen for individuals diagnosed with schizophrenia." (PMID 38998877, 2024). "In this post-hoc analysis, patients with schizophrenia in the acute phase were divided into an elevated-prolactin group and a normal-prolactin group." (PMID 39267697, 2024).
schizophrenia (continued). "When analyzed by gender, mean prolactin values were found to be significantly higher in female schizophrenia patients than in male schizophrenia patients (p=0.005)." (PMID 38899233, 2024). "This study aims to analyze the dynamic alterations in PANSS total scores and prolactin levels in patients with schizophrenia treated with risperidone, along with the influencing covariates." (PMID 38399363, 2024). "In summary, our study showed that pharmacogenomics-guided treatment of antipsychotics significantly improved the clinical outcomes in terms of drug efficacy and adverse effects of prolactin elevation in patients with schizophrenia." (PMID 37801319, 2023). "The recurring theme found in this analysis was that abnormally high levels of prolactin will decrease upon cessation of certain antipsychotic medications prescribed for schizophrenia and other psychotic diagnoses." (PMID 38143631, 2023). "More recent studies have investigated the use of prolactin-raising antipsychotics in terms of the rate of low-energy fractures in people with schizophrenia." (PMID 37759839, 2023). "Despite finding PRL levels within the range considered normal, there were noticeable differences between PRL levels in patients with schizophrenia according to the type of symptoms of the disease (paranoid, schizoaffective, or disorganized)." (PMID 37047464, 2023). "We consider the effects of the disease itself (schizophrenia), and antipsychotics on sex hormone levels and prolactin levels." (PMID 37047464, 2023). "Some behaviors in patients with schizophrenia are risk factors for BC, including obesity, childlessness, and use of anti-schizophrenia drugs leading to elevated prolactin levels." (PMID 37656762, 2023). "In summary, antipsychotic medication used to treat schizophrenia elevates prolactin levels, with some drugs doing so more than others." (PMID 37759839, 2023). "Because of its central role in working memory and executive functions, the PrL is thought to function as a central hub in the brain circuitry, mediating symptoms of psychiatric disorders such as depression and schizophrenia." (PMID 37500828, 2023). "Available evidence suggests elevated serum prolactin (PRL) levels in olanzapine (OLZ)-treated patients with schizophrenia." (PMID 36313772, 2022). "Risperidone (Ris) is a common antipsychotic drug used for treating schizophrenia; however, increases in PRL levels are common after long-term administration, leading to serious adverse reactions, such as amenorrhea, galactorrhea, anovulation and infertility." (PMID 35865960, 2022). "Despite extensive and numerous studies on metabolic disorders and HPRL in schizophrenia, only a few studies have focused on the metabolic levels of long-term hospitalized schizophrenia patients and their relationship with PRL levels." (PMID 36329924, 2022). "A study of new-onset drug-naive schizophrenia reported that women had higher mean PRL levels than men." (PMID 36329924, 2022). "Evidence for increased prolactin levels in persons with schizophrenia treated with antipsychotics has been found for decades." (PMID 35806096, 2022). "This article is aimed at analyzing the factors influencing comorbid type 2 diabetes mellitus (T2DM) on prolactin (PRL) levels in long-term hospitalized patients suffering from schizophrenia." (PMID 36329924, 2022). "Some studies have investigated the influence of prolactin-increasing antipsychotics on the bone mineral density of patients with schizophrenia." (PMID 35105317, 2022). "The present study also reported a positive protective effect of prescription aripiprazole upon PRL levels in chronic long-term hospitalized patients with schizophrenia." (PMID 36329924, 2022). "For example, dysregulations of insulin, cortisol, glucagon, glucagon-like peptide 1, cholecystokinin, adiponectin, ghrelin, leptin, orexin, prolactin, and oxytocin have been observed during treatment with antipsychotics among persons with schizophrenia." (PMID 35806096, 2022).